Y_RNA (Y RNA )
Gene: Miscellaneous RNA gene on chromosome 16 (15,150,697 to 15,150,796, forward strand). Ensembl gene ENSG00000207294.
Homologues: Orthologues: chimpanzee Y_RNA (98% identical), macaque Y_RNA (93% identical), dog Y_RNA (80% identical), pig Y_RNA (80% identical). Paralogues in human: Y_RNA (100% identical), Y_RNA (98% identical), Y_RNA (84% identical), Y_RNA (83% identical), Y_RNA (82% identical), RNY3 (81% identical), Y_RNA (81% identical), RNY3P1 (80% identical), RNY3P4 (80% identical), Y_RNA (80% identical), RNY3P11 (79% identical), Y_RNA (79% identical), and 92 more.